PBRM1 (polybromo 1)
Diseases named in the same sentence as PBRM1 in open-access papers (continued):
Sharing a sentence is not in itself a finding about the gene and the disease.
cancer (continued). "(d) Others: PD-1/PD-L1 inhibitors have synthetic lethal effects in ARID1A- and PBRM1-deficient cancers." (PMID 36371186, 2022). "In the future, it will be valuable to reveal different mechanisms by which mutations in PBRM1 exert diverse effects on cancer progression and the TME among ccRCC cell lines." (PMID 35936012, 2022). "A pan-cancer study on PBRM1 mutations revealed an association of PBRM1 mutation with OS (HR: 1.24, p = 0.47) in 189 patients with mRCC treated with ICI." (PMID 35775004, 2022). "As with non-cancer-derived cell lines, we found that loss of PBRM1 leads to a reduction in the G2/M population at late time points when compared with the nontargeting siRNA (siCON)-treated Caki-1 cells." (PMID 35902118, 2022). "The Cancer Genome Atlas project revealed mutations in bromodomain-containing genes, such as Polybromo-1 (PBRM1), in both ccRCC and some nccRCC subtypes." (PMID 34359554, 2021). "In primary and advanced RCC, the expression characteristics of cancer cell subsets and immune escape are associated with PBRM1 mutations." (PMID 34149798, 2021). "To evaluate the prevalence of PBAF complex mutations, we queried the pan-cancer TCGA atlas (n = 10,359) and analyzed all three genes in the complex (PBRM1, ARID2, and BRD7)." (PMID 32820162, 2020). "As PBRM1 deficiency has been shown to boost the efficacy of immune checkpoint drugs in ccRCC and other cancers, the disruption of H3K14ac recognition by PBRM1 has the potential to increase the response rate of immunotherapy and warrants further investigation." (PMID 30585695, 2019). "CREBBP and EP300 appeared to be widely mutated in multiple cancer types at a low to modest frequency (0.2–13.5% and 0.2–14.8%, respectively) and PBRM1 was highly mutated in KIRC (40.1%)." (PMID 30760718, 2019). "At a pan-cancer level, except for PBRM1, the most common mutation category of HAMPs was missense mutation (53.0–77.5%) and the dominant mutation type was heterozygous mutations (67.2–89.0%)." (PMID 30760718, 2019). "Other novel, highly scoring gene pair predictions that included cancer associated genes included PARP1 with PBRM1, BRCA2, ARID1A and APC as well as PIK3CA with MAP2K1, ABL1 and EGFR." (PMID 30995217, 2019). "Future studies to dissect the role of PBRM1 in different cancer types would be helpful to better understand the mechanisms of PBRM1 truncation mutations and tumorigenesis." (PMID 27556922, 2016). "Among these cancer types, PBRM1 is one of the most frequently mutated and studied genes in ccRCC than any other cancer types." (PMID 27556922, 2016). "Nevertheless, similar effects of PBRM1 in diverse cancer cells implicated its fundamental role in cell cycle regulation and tumorigenesis." (PMID 25978027, 2015). "We also confirmed the same point mutations in KRAS and PBRM1 in the DNA of the primary carcinoma by Sanger sequencing." (PMID 26669280, 2015). "It is most likely that these mutations are inactivating, as loss of PBRM1 expression and gene deletion are noted in several cancers and cell lines." (PMID 24622842, 2014). "A number of missense mutations were identified in the gene encoding BAF180 (PBRM1) in cancer cells, some of which are predicted to have relatively little effect on protein folding and stability." (PMID 24613357, 2014). "We further investigated available proteomic datasets in the cancer cell line encyclopedia (CCLE) to explore whether downregulated centromere proteins are a general feature of PBRM1 loss." (PMID 40011561, 2025). "Therefore, cancer-associated mutations can disrupt the regulatory roles held by PBRM1 in multiple aspects of cellular homeostasis." (PMID 38460939, 2024).
cancer (continued). "Cancers with a loss of PBRM1 are more responsive to DNA damage and immune checkpoint inhibitors, suggesting that small molecule inhibitors selective for PBRM1 would be therapeutically useful." (PMID 38390898, 2024). "These discrepancies in clinical response may be explained by individual PBRM1 mutations not being functionally equivalent; instead, different classes of PBRM1 mutations may have unique impacts on overall protein stability and activity in the context of cancer." (PMID 38460939, 2024). "However, the biophysical attributes and cellular implications of cancer-associated PBRM1 bromodomain missense variants remain largely unexplored." (PMID 38460939, 2024). "Because of the frequent mutations in ARID2 and PBRM1 in some cancers, we explored whether loss of either subunit altered NRF2 signaling." (PMID 38358974, 2024). "Despite the loss of PBRM1 protein expression in many cases of cancer-associated PBRM1 mutations, this study highlights the clinical relevance of cancer-associated PBRM1-BD4 missense variants with variable stability and histone Kac binding compared to the WT protein." (PMID 38460939, 2024). "As PBRM1 plays context-dependent roles in several aspects of cancer biology, elucidating the effects of cancer-associated PBRM1 bromodomain missense mutations on protein stability and biochemical activity is essential to further delineate the roles of PBRM1 in cancer and ICB therapeutic response." (PMID 38460939, 2024). "Further exploration of PBRM1 loss in these cancers could provide a mechanism behind its effects on NRF2 activity in these cancers." (PMID 38358974, 2024). "PBRM1 is mutated at high rates in renal clear cell carcinomas, among other cancers." (PMID 36605718, 2022). "On the basis of these results, the PBRM1 mutation has an important role in immunotherapy efficacy, which could predict clinical benefit of cancer patients." (PMID 36699446, 2022). "The SWI/SNF genes, ARID1A, ARID1B, ARID2, SMARCA4, SMARCB1, and PBRM1 were mutated in up to 21.8% of all the cancers, and SWI/SNF mutation carriers had significantly higher TMB values as well as higher TMB-H and MSI-H proportions than their SWI/SNF-non-mutant counterparts in several malignancies." (PMID 36371186, 2022). "In addition, we did not conducted a part of in vitro and in vivo experiments to verify the relationship between PBRM1 mutation and immunotherapy in cancer." (PMID 36699446, 2022). "In addition, PBRM1 mutation can affect the immune microenvironment and the activation of immune-related pathways in cancer patients." (PMID 36699446, 2022). "Thus, the inhibition of EZH2 using tazemetostat or GSK126 causes synthetic lethality in ARID1A-, SMARCA4-, SMARCB1-, PBRM1-deficient cancers." (PMID 36371186, 2022). "PBRM1 loss in cancer cells was observed in 148 (34.8%) patients." (PMID 35205810, 2022). "Furthermore, they showed that PBRM1 phosphorylation by the serine/threonine kinase ATM is required for both repair and transcriptional silencing and cannot be rescued by a cancer-associated PBRM1 mutant." (PMID 32977645, 2020). "PBRM1‐deficient cancer cells exhibit a weakened HIF transcriptional signature." (PMID 30585695, 2019). "Indeed, PBRM1 inactivation increases sensitivity of cancer cells to T cell-mediated killing and truncating loss-of-function mutations in PBRM1 is associated with increased response rates to anti-PD-1 or anti-PD-L1 in ccRCC patients." (PMID 31113486, 2019). "In contrast, PBRM1 showed high-frequency, cancer type-specific mutations in KIRC (40.1%)." (PMID 30760718, 2019). "While mutations in BAP1 and PBRM1 have been shown to be associated with poor cancer-specific survival, the frequency of these mutations (and their clinical relevance) in metastatic ccRCC tumors is unknown." (PMID 28327121, 2017). "Moreover, the Cancer Genome Atlas database (TCGA) reveals co-mutation of PBRM1 and SETD2 in multiple tumors despite the low mutation frequency of both genes in these cancers." (PMID 27191891, 2016).
cancer (continued). "PBRM1 is found to be highly mutated in several cancer types." (PMID 27556922, 2016). "The gene encoding BAF180 (PBRM1) is frequently mutated in cancer." (PMID 25066234, 2014). "However, ∼33% of PBRM1 mutations in cancer are missense and cluster within its bromodomains." (PMID 38460939, 2024). "Moreover, our results uncover PBRM1-mediated molecular mechanisms disrupted by cancer-associated missense mutations and the potential for select missense variants retaining WT protein functions to serve as therapeutic targets in cancer." (PMID 38460939, 2024). "Moreover, our data indicate that further characterization of PBRM1 bromodomain missense variants in the context of cancer pathogenesis and therapeutic response is mechanistically and clinically warranted to improve precision medicine approaches for cancer treatment." (PMID 38460939, 2024). "Therefore, understanding the effects of specific PBRM1 bromodomain missense variants on protein stability and function can inform precision medicine approaches targeting PBRM1 and its bromodomains in the context of cancer therapy." (PMID 38460939, 2024). "However, it remains incompletely unclear whether PBRM1 mutations correlate with ICI response in pan-cancer." (PMID 36699446, 2022). "Cancer cells often show evidence of replication stress, and this can lead to DNA damage that could contribute to the improved immunotherapy response in patients with PBRM1-deficient tumors." (PMID 35902118, 2022). "Finally, Arid2, together with Pbrm1, is linked to cancer cell immunotherapy resistance." (PMID 32977645, 2020). "Together, these data suggest that reliance on the SAC in PBRM1 KO cancers represents a therapeutic vulnerability that can be clinically exploited." (PMID 40011561, 2025). "In cancer, subunits of chromatin remodelers are frequently mutated–for instance, ARID1A, ARID1B, and PBRM1 (components of the SWI/SNF complex) are mutated in various cancers." (PMID 41234540, 2025). "Next, we used the TIMER database to analyze the cancer data from The Cancer Genome Atlas (TCGA) for PBRM1 expression levels." (PMID 40093909, 2025). "Polybromo 1 (PBRM1) is a PBAF-specific subunit, and inactivating mutations in PBRM1 have been reported in several cancers, including PDAC." (PMID 40454484, 2025). "For instance, PBRM1, ARID2, and BRD7, which encode subunits uniquely expressed by the pBAF complex, have been found to be mutated in approximately 1%–8% of human cancers." (PMID 41387924, 2025). "A critical question is what the fundamental functions of PBRM1 are, which, when lost, contribute to the development or evolution of cancer." (PMID 40011561, 2025). "Frequent alterations in PBRM1 have been observed across various human cancers, but its alteration rate is particularly high in ccRCC, with approximately 40% of tumors harboring damaging PBRM1 alterations." (PMID 38371625, 2024). "Our analysis revealed AS alterations of Polybromo-1 (PBRM1) exon 27 (E27) in most types of cancer tissues." (PMID 39375538, 2024). "Up to 25% of human cancers carry mutations in at least one of nine SWI/SNF subunit genes including SMARCA1 and 2, SMARCB1, ARID1A/B, PBRM1, and ARID2." (PMID 38085333, 2024). "Our analysis demonstrated that cancer-associated PBRM1-BD4 missense variants variably impaired the cellular stability and histone Kac binding of full-length PBRM1 and diminished PBRM1-mediated cell growth suppression." (PMID 38460939, 2024). "The identification of AS alterations of PBRM1 E27 in cancer and its role in cancer immune evasion raises questions about their impact on patients with cancer." (PMID 39375538, 2024). "Further studies should aim at investigating the AS pattern alteration drivers of PBRM1 E27 in cancer tissues as well as the unique splicing landscapes of ccRCC compared to other cancer types." (PMID 39375538, 2024). "In this study, a comprehensive analysis of AS in key cancer driver genes uncovered splicing alterations of PBRM1 E27 in most cancer types." (PMID 39375538, 2024).
cancer (continued). "Next, we calculated the mean change in PSI value in pan-cancer tissues compared with that in normal tissues and found that PBRM1 E27 exhibited the highest mean |ΔPSI| value." (PMID 39375538, 2024). "The promising results obtained with PB16 suggest that GNE-235 and other PBRM1-selective inhibitors should be further explored for anti-cancer effects as single drugs and in combination with DNA damaging agents and checkpoint inhibitors." (PMID 38390898, 2024). "Using this approach, we discovered the prevalent splicing alterations of PBRM1 E27 in cancer tissues." (PMID 39375538, 2024). "PBRM1 is frequently altered in various cancers particularly ccRCC with ~40% of tumors harboring damaging PBRM1 alterations." (PMID 38371625, 2024). "Overall, these results indicate that the inclusion of E27 in PBRM1 enhances PD-L1 expression in cancer cells." (PMID 39375538, 2024). "The results showed that alterations in |ΔPSI| values of PBRM1 E27, by more than 0.15, occurred in over 49% patients with cancer, which was the highest frequency among AS events." (PMID 39375538, 2024). "As PBRM1-BD4 is targeted by missense mutations in cancer, our findings shed light on the importance of BD4 in the mutational landscape of PBRM1 and its involvement in histone Kac interactions and cellular function." (PMID 38460939, 2024). "PRCC also displays mutations in previously studied cancer-related pathways; these include NF2 (Hippo pathway), SMARCB1 and PBRM1 (SWI/SNF complex), and chromatin modifier pathways (SETD2, KDM6A, and BAP1)." (PMID 38162463, 2023). "Shared recurrent mutations in both NDD and cancer included those localized to the C-terminal domain of SMARCB1, the SMARCA4 N terminus, as well as within PBRM1 and ACTB subunits." (PMID 37500730, 2023). "ARID1A is mutated in 9% of all cancers based on a survey of 24 whole exome studies across 18 different cancer types, followed by PBRM1 (4%) and SMARCA4 (3%)." (PMID 38275587, 2023). "Surprisingly, little is known about the functional involvement of PBRM1 in integrating chromatin remodeling with DNA damage resistance and immune evasion in cancer cells." (PMID 36445328, 2023). "Mutation of PBRM1 BAH1 and BAH2 residues that were predicted to be important for histone interaction as well as mutation of residues that occur in various cancers, reduced histone-BAH domain interactions in vitro." (PMID 37394010, 2023). "Inactivation of PBRM1 in human cancers thereby contributes to replication stress and confers synthetic lethality to DNA repair inhibitors targeting PARP and ATR." (PMID 36445328, 2023). "Each of these cases also carried other germline mutations (PBRM1, C7 and MYH9, BRCA1, ANKRD26) of which BRCA1 and ANKRD26 are cancer predisposition genes." (PMID 37869077, 2023). "From our initial histone binding screens and structural homology modeling, we identified several residues in the PBRM1 BAH domains that are likely involved in histone binding, including some residues that are mutated in cancer." (PMID 37394010, 2023). "The most frequent mutations in a large panel of 1123 cancer-related genes in the overall population of RCC patients were VHL (51%), PBRM1 (35%), BAP1 (16%), KMT2D (15%), PTPRD (15%), and SETD2 (15%)." (PMID 37427096, 2023). "We subsequently explored the association of PGAM1 mutations with common cancer progression genes, such as VHL, PBRM1, and SETD2." (PMID 37847178, 2023). "Among the six SWI/SNF genes, ARID1A and SMARCB1 were, respectively, the most and least frequently mutated genes in the majority of the cancer types (ARID1A, 10.7%; SMARCA4, 6.0%; ARID1B, 4.7%; ARID2, 4.0%; PBRM1, 3.5%; SMARCB1, 1.3%)." (PMID 36371186, 2022). "This correlation implied the orchestrated expression of PBRM1, raising the possibility that the cancer cells and their microenvironment interact in ccRCC." (PMID 35205810, 2022).
cancer (continued). "Several genomic studies have identified various components of the SWI/SNF chromatin remodeling complex, such as polybromo- and BRG1-associated factors (PBAF), which contains PBRM1, ARID2, and BRD7, as frequently mutated genes across cancer types." (PMID 35703181, 2022). "While bromodomain inhibition was not as effective as ATPase inhibition at curbing growth of some SWI/SNF mutant cancers, PFI-3, a small molecule selective for the SMARCA4/SMARCA2/PBRM1 bromodomains, sensitized cancer cells to DNA-damaging agents." (PMID 35323214, 2022). "A high frequency of dysregulation in the chromatin remodelling pathway, especially PBRM1‐inactivating mutations and the PBRM1‐c‐JUN‐VIM axis, served as an important role of cancer invasion and was associated with poor patient outcomes in DPC." (PMID 36178086, 2022). "Another group of accessory factors mutated at high frequencies in cancer are bromodomain-containing proteins BRD7, BRD9, and PBRM1." (PMID 36605718, 2022). "A positive correlation between PBRM1 expression in cancer cells and endothelial cells was confirmed (correlation coefficient = 0.834, p < 0.001)." (PMID 35205810, 2022). "The mutational rates and variation types of six SWI/SNF complex genes (ARID1A, ARID1B, ARID2, SMARCA4, SMARCB1, and PBRM1) were analyzed retrospectively by integrating next-generation sequencing data of 4591 cases covering 18 cancer types." (PMID 36371186, 2022). "PBRM1 expression in vascular endothelial cells correlated with the expression of cancer cells (correlation coefficient = 0.834, p < 0.001)." (PMID 35205810, 2022). "PBRM1 has been reported to protect cancer cells under high-stress conditions, and patients with ccRCC harboring PBRM1 mutations show better responsiveness to PD-1 inhibitors." (PMID 35625960, 2022). "A study using a genome-wide CRISPR–Cas9 screen found that PBRM1 expression was inversely correlated with the expression of T-cell cytotoxicity genes in a variety of cancers." (PMID 35928964, 2022). "We demonstrated that PBRM1 expression of cancer cells correlated with histomorphological features of ccRCC and correlated with the expression of vascular endothelial cells." (PMID 35205810, 2022). "Recent genomic advances using exome sequencing revealed that the PBRM 1 gene encoding the protein polybromo-1, which is a subunit of the SWI/SNF chromatin remodeling complex, is a second major ccRCC cancer gene, following the VHL gene." (PMID 35205810, 2022). "miR-21 affects lipogenesis, NAFLD, and cancer induction by its inhibitory effect on human polybromo-1 (HPB1) and PPAR-α." (PMID 34426744, 2021). "Our results further demonstrate that MUC1-C integrates activation of PBRM1 with the regulation of antioxidant genes, ROS levels, pluripotency factor expression and the cancer stem cell (CSC) state." (PMID 34163028, 2021). "We used the TIMER database to analyze the cancer data in The Cancer Genome Atlas (TCGA) database for PBRM1 expression levels." (PMID 34447697, 2021). "SWI/SNF subunits are the most commonly mutated chromatin-regulatory complexes in human cancer, mutated in 19.6% cancers, with subunits ARID1A, PBRM1, SMARCA4, and ARID2 already part of routine cancer diagnostics." (PMID 34944438, 2021). "PBRM1- and SMARCA2-expression were lost in the carcinoma but retained in the associated high-grade biliary intraepithelial neoplasia." (PMID 34118935, 2021). "For the MSK-IMPACT cohort, we restricted our analysis to 189 ccRCC patients and 2936 patients treated with immunotherapy comprising 11 other cancer types that had a minimum of 50 patients and 5 PBRM1 or ARID2 mutants." (PMID 32820162, 2020).